IL6 (interleukin 6)
Diseases named in the same sentence as IL6 in open-access papers (continued):
Sharing a sentence is not in itself a finding about the gene and the disease.
tumor (continued). "Moreover, IL-37 reduces tumor promoting cytokines including IL-6, IL-1β and TNF-α produced by both tumor cells and immune cells." (PMID 37928545, 2023). "The percentage of MDSCs in the spleen and blood was not different after anti-IL-6 treatment alone when compared to the tumor-bearing group." (PMID 37108179, 2023). "Tumor cells secrete various factors that stimulate osteoclast-mediated bone resorption, and there are studies showing that IL-1, IL-6, IL-8, tumor necrosis factor (TNF)-α, and transforming growth factor (TGF)-β are secreted by tumor cells and contribute to osteoclast-induced bone resorption." (PMID 36795736, 2023). "Additionally, IL-19 involved the role of MMP2, IL-6, MMP9, IL-1β, CXCR4, fibronectin, and TGF- β for tumor development." (PMID 37675062, 2023). "They found that MEK inhibitors not only had a direct killing effect on tumor cells, but also promoted tumor recognition by CD8+ T cells, increased the expression of cytokines such as IFN?, IL12, IL6 and TNFa, and prevented T cell depletion by downregulating PD-L1, CTLA-4, TIM-3 and LAG-3." (PMID 37016422, 2023). "In support of this conclusion, we found a significant increase in pro-inflammatory cytokines, such as IFNγ and IL-6, at the later stages of tumor growth compared to early stages in HFD-fed mice, correlating with the increased tumor size in HFD-fed mice at 5 wpi." (PMID 36675341, 2023). "NR3C1 amplification, along with IL-6 and SRPX suppressions, were detected in tumor." (PMID 36675190, 2023). "The results reported a reduction in tumor-induced proinflammatory cytokines IL-6, TNF-α, and IL-1β, and no adverse effects or toxicity in mice has been found." (PMID 37570775, 2023). "Thus, pharmacological inhibition of LDHA suppressed tumor growth along with CAF reduction and reversed the immunosuppressive status of CAF-rich PDAC tumors through reductions in the levels of lactate and IL-6." (PMID 37733442, 2023). "Moreover, CAFs also release MMPs and IL-6, IL-10, TGF-β, C-C motif chemokine ligand 22 (CCL)-2, and CCL5, which stimulate tumor growth and block the natural immune response against cancer." (PMID 36831498, 2023). "M2 macrophages secrete a large amount of IL-6, which subsequently enhances 3-phosphoinositide-dependent protein kinase 1 (PDPK1)-mediated phosphoglycerate kinase 1 (PGK1) threonine (T) 243 phosphorylation in tumor cells." (PMID 37012233, 2023). "We speculate that sustained IL-6/IL-6Rα signaling during EMT-MET plasticity states further drives the modification of MPE environment, amplifying the aggressive MPE tumor state." (PMID 37063842, 2023). "Inflammatory cytokines including TNF-α, IL-6, IFN-γ, and chemokines could exert antiproliferative and pro-apoptotic effects on tumor cells, or indirectly modulate the TIME." (PMID 37190266, 2023). "BC tumor-derived SEVs can induce an M1 proinflammatory response in macrophages through the activation of NFκB, which stimulates the production of inflammatory cytokines including GCSF, IL-6, IL-8, IL-1β, CCL2, and TNF-α." (PMID 37108371, 2023). "IL-6 also activates human CD14+ peripheral blood nuclear cells through the STAT3 pathway producing CCL18 and TGFβ, which leads to the induction of the EMT with tumor-promoting effects." (PMID 37190141, 2023). "As CRP production is stimulated by IL-6, an increase in CRP levels early after ICI administration may reflect the activation of immune cells, which can enhance anti-tumour immunity." (PMID 39516365, 2023). "Some proinflammatory cytokines, such as IL-6, IL-1β, and TNF-α, are secreted by macrophages, which may contribute to tumor-promoting inflammation." (PMID 37211559, 2023). "CAFs could interact with tumor cells by releasing secreted proteins such as transforming growth factor β (TGF-β), insulin-like growth factor (IGF) and interleukin-6 (IL-6), regulating immune feedback or remodeling of the extracellular matrix, etc.." (PMID 37441535, 2023).
tumor (continued). "In both tumor models, dual IL-6 and CTLA-4 blockade significantly inhibited tumor growth." (PMID 36881480, 2023). "There are also studies focusing on specific cytokines, and the results all support that circulating cytokine levels have the potential to reflect the state of the tumor immune microenvironment and the clinical outcomes of ICI therapy, particularly IL-6 and INFγ levels." (PMID 37002211, 2023). "IL‐6 activated STAT3‐signalling in skeletal muscles and adipose tissues resulted in tissue atrophy of CHX207 mice, similar to previous observations in C26‐tumour‐bearing mice." (PMID 36351437, 2023). "Previous studies have shown that TAMs in HCC tumor stroma produce various proinflammatory cytokines, including TNF-α, IL-β, IL-6 and IL-23, which induce the expansion of CD4+ Th17 cells, according to the overexpression of PD-L1, CTLA4 to inhibit antitumor immunity." (PMID 37745297, 2023). "IL-6 promotes the activation of the STAT3 pathway, thereby promoting tumor cell proliferation." (PMID 38136358, 2023). "Finally, to strengthen relevance of these findings, we tested also combinations on MM cells co-incubated with cytokines mixtures (IL-6 and IGF-1) mimicking bone-marrow milieu: anti-tumor activity was kept also in this context." (PMID 36830052, 2023). "All non-PBS experimental groups produced detectable TNFα and IL-6 in the plasma from day 5 to day 26, suggesting the activation of human neutrophils upon tumor stimulation." (PMID 37080958, 2023). "Importantly, tumor cells can secret cytokines, including TGF-beta, IL-6, IL10, and VEGF, which commonly lead to the upregulation of PD-1/PD-L1 expression to evade immune detection." (PMID 37880708, 2023). "In addition, other factors secreted by microglia residing within the GBM, such as the epidermal growth factor (EGF), IL-1β, IL-6, and IL-8, can activate receptors on GBM cells, promoting tumour invasion." (PMID 36675073, 2023). "Clinical data indicated that targeting IL-6 can mitigate the immune-related adverse event without compromising the overall tumor response to ICB." (PMID 37605139, 2023). "AP in cancer cells by increasing the secretion of cytokines and immune modulatory factors, including IL6, IL10, TGFβ, and VEGF, and activating survival/signaling pathways such as PI3K-Akt-mTOR, sustains immunosuppression and promotes tumor progression, metastasis, and therapy resistance." (PMID 37626858, 2023). "Consistent with this, the levels of IFN-γ, TNF-α and IL-6 significantly increased in the serum of mice from the Bif@PAu-NPs + NIR + GM-CSF group compared to the other groups, indicating that a robust anti-tumor immune response triggered by the combination treatment." (PMID 37872620, 2023). "Here, the increase of IL-2, IL-6 were found in the primary gastrointestinal cancer patients without anti-tumor treatments." (PMID 36765353, 2023). "The downregulation of amphiregulin, IL-6 and EPHA2 suggests interference with pathways critical for tumor growth and progression and may explain the pronounced effect seen in the in vivo study." (PMID 37803074, 2023). "However, the inhibition of IL-6 and IL-8 in TNBC cell lines decreased cell survival as well as colony formation, and prevented tumor growth in vivo." (PMID 37340387, 2023). "Notably, tumor immune‐related cytokines, including tumor necrosis factor (TNF)‐α, IL‐1β, IL‐2, IL‐6, IL‐17, CD4+/CD8+, IFN‐α, and IFN‐γ, were determined." (PMID 36951443, 2023). "While IL-4, IL-6, and IL-10 demonstrated a rise from baseline to tumor response, none of these changes reached statistical significance." (PMID 38022654, 2023).
tumor (continued). "First, we found that the expression level of KLF7 is higher in PCa tissues of patients, and the expression of KLF7 is positively correlated with tumour-promoting gene IL-6, while it is negative correlated with another tumour-suppressor gene p21." (PMID 37170248, 2023). "Interestingly, orthotopic LLC tumors strongly increased serum IL-6 levels, which were drastically reduced by IV BCG treatment, coinciding with the lower tumor burden observed in these mice." (PMID 37794033, 2023). "For example, TNF, IL-6, and IFN- γ upregulate PD-L1 expression in tumor cells." (PMID 36941614, 2023). "However, interleukin 6 (IL-6) and TNF can enhance tumor proliferation and metastasis which needs exact considerations." (PMID 37238916, 2023). "The analysis of IL-6 levels in the dynamics of neoadjuvant therapy in IBC patients revealed that the first subgroup still had elevated levels, typically seen during active tumor growth." (PMID 36873124, 2023). "For example, strawberry (Fragaria ananassa) methanolic extracts have anti-inflammatory activity, reducing the levels of the tested inflammatory markers (NF-kB, pIkBa, TNF-α, IL-1b, IL-6, and iNOS) in RAW macrophages, which is an Abelson murine leukemia virus-induced tumor." (PMID 36771154, 2023). "Whereas these vesicles triggered IL-6 and CXCL8 expression, further studies will be required to clarify how such induction may impact tumor progression." (PMID 37833751, 2023). "Furthermore, IL-6 was also found to induce the production of VEGF and facilitate angiogenesis in the residual tumor, leading to tumor progression." (PMID 36831664, 2023). "IL-6 and OSMR play a role in tumor proliferation by activating transcription factors." (PMID 37671166, 2023). "Interestingly, the introduction of IL-6 and IL-8 shRNAs into CCL18-activated NBFs significantly increased the chemotherapy-induced apoptosis of cocultured tumor cells." (PMID 36418470, 2023). "Several mouse studies have shown significantly (17 experiments) or non-significantly (4 experiments) improved tumour control or survival with upfront anti-IL-6 plus ICI compared to ICI alone 102,104–110." (PMID 37173424, 2023). "Many studies have uncovered that certain microbes could not only influence cytokines such as IL‐6 and TNF‐a directly or indirectly, but also activate the NF‐κB pathway or STAT3 pathway to promote tumor progression." (PMID 38868430, 2023). "IL-6 protein was significantly higher in pre-treatment plasma samples from RCC (IMmotion150) patients compared with healthy controls and correlated significantly with tumor IL6 mRNA (r = 0.32, p < 0.0001)." (PMID 36599350, 2023). "Since IL-6 promotes gliomagenesis and it is a known SASP factor, blocking IL-6 could help attenuate tumor growth in the previously radiated microenvironment." (PMID 38030881, 2023). "Besides, we find down-regulation of tumor-derived GLI2 decreases the expression of tumor-derived PDL1 and IL6, and it also leads down-regulation of NK cell-derived PD1 and TIM-3, all of which are restored by adding TGF-beta active protein." (PMID 38159250, 2023). "MSC-derived IL-6 induces endothelin-1 (ET-1) secretion from cancer cells, which activates the AKT and ERK pathways in endothelial cells to promote endothelial cell recruitment and tumor neovascularization in gastrointestinal cancer cells." (PMID 37189649, 2023). "CAFs accelerate the development of tumours by secreting TGF-β and IL-6." (PMID 37927475, 2023). "It has been reported that IL-6 present in the TME can induce non-CSCs to transform into tumor stem cells." (PMID 37886168, 2023).
tumor (continued). "IL‐6 activates the signal transducer and transcriptional activator 3 (STAT3) through the JAK/STAT pathway, which, in turn, encourages inflammatory responses and the development of tumours." (PMID 38041544, 2023). "IL-6 level during therapy in IBC patients remained high, which occurs in active tumor development." (PMID 36873124, 2023). "Furthermore, IL-6 in turn increased the EIF4A3 and CCL2 levels within tumor cells in a positive feedback mechanism, further enhancing tumor cSERPINE2 biogenesis and promoting the recruitment of TAMs." (PMID 36797769, 2023). "Since high IL-6 induces MDSCs and suppresses anti-tumor immunity, reflected by reduced CD8+ lymphocyte counts, it is possible that eribulin is not sufficiently effective in patients with high IL-6 levels due to a poor tumor immune microenvironment." (PMID 37733188, 2023). "The pro-tumor activity of IL-10 relied, at least in part, on the over-expression of SOCS-3 (Suppressor of Cytokine Signaling 3) that in turn inhibited the anti-tumoral IL-6 signaling pathway in macrophages co-cultured with metastatic tumor cells." (PMID 37835437, 2023). "Preclinical studies have demonstrated the efficacy of STAT3 pathway inhibitors, such as Stattic, C188-9, OPB-31121, OPB-51602, AZD9150, and STAT3 decoy oligonucleotide, as well as drugs targeting IL6/IL6R, including Siltuximab, Tocilizumab, and Olamkicept, across various tumor models." (PMID 37784157, 2023). "Altogether our findings suggest that the presence of SCF and IL-33 in CRC tissues favor the accumulation of a connective tissue-like MC phenotype which through the production of IL-6 and TNF-α contribute to the establishment of an inflammatory tumor microenvironment." (PMID 37730723, 2023). "Given the predominance of IL-10, IL-6, IL-1β and VEGF in MDSC secreted supernatant and increased expression of corresponding receptors on tumor cells following co-culture with MDSC and MDSC-supernatant, next we tried to validate the role of individual cytokine in induction of MDR." (PMID 38304256, 2023). "Serum interleukin 6 (IL-6) decreased the expression of PTPRO by activating signal transducer and activator of transcription 3 (STAT3)/c-MYC/miR-25-3p axis, leading to PD-L1-induced immunosuppression to promote tumor growth." (PMID 38155974, 2023). "Notably, the release of cytokines such as IL-6 and IL-10 promotes an immunosuppressive TME, facilitating tumor escape from immune surveillance." (PMID 38035068, 2023). "Correlation between IL-6, CA-125, or HE4 with tumor resectability." (PMID 37792745, 2023). "An anti-tumor effect was mediated via the suppression of HIF-1α, while the others were anti-inflammatory and anti-fibrotic effects, such as the downregulation of NF-κB, IL-6, and TGF-β." (PMID 37511305, 2023). "Moreover, chemotactic cytokines such as IL-6 or CXCL11 secreted by senescent endothelial cells can directly stimulate proliferation and aggressiveness of tumor cells." (PMID 36978029, 2023). "A ketogenic diet implemented in C26 tumor-bearing mice resulted in preserved body, muscle, and carcass weight and markedly lowered tumor weight and plasma IL-6 levels, indicating a negative correlation between blood ketone bodies and tumor weight." (PMID 37755304, 2023). "In cohort B, RNA-seq analysis demonstrated higher IL-6 expression on tumor cells of non-responders, along with a shorter PFS (p<0.05) and enrichment of the purinergic pathway." (PMID 37852738, 2023). "The use of the IL-6-enriched Ov-MSC-CM promoted cell proliferation and tumor sphere formation." (PMID 38049868, 2023). "Additionally, IL6 and CCL2 were induced in CAFs upon co-culture with patient matched tumor organoids to a greater extent than in NFs along with the activation of NFκB target genes." (PMID 37460545, 2023).
tumor (continued). "In contrast, the pro-tumor TANs have higher levels of Arginase 1 (Arg1), CD206, Ym1, IL-6, CCL17, CXCR4, neutrophil elastase (NE), matrix metalloproteinase 9 (MMP9), vascular endothelial growth factor (VEGF), and the neuropeptide prokineticin 2 (PROK2, also known as Bv8)." (PMID 37496019, 2023). "In addition, the greatest significant reduction in IL-6 (p < 0.05) was observed at the 12.5 mg/kg dose, which was where the greatest reduction in F3II tumor volume was achieved." (PMID 38137888, 2023). "In contrast, IFNGR signaling in non-endothelial cells had the opposite effect of promoting tumor growth, consistent with the counter-regulatory production of IL6 elicited by IFNγ-mediated induction of IDO1." (PMID 37182174, 2023). "The increase in secretion of IL-6 protein in conditioned media from Kin1-NULL cells was confirmed by ELISA, while bulk tumor RNA analysis of Kin1-WT and Kin1-NULL tumors showed changes in IL-6-related genes, with an increase in Il6, Il6ra, and Il6st found in Kin1-NULL tumors." (PMID 36883731, 2023). "However, from the perspective of immunosuppression, immunosuppressive factors such as IL-6, TGF-β, and IL-10 produced from tumor cells attenuate the activation level of DCs." (PMID 37553633, 2023). "Skin KS had higher IL-6 and IL-10 gene expression compared to normal tissue, whereas GI KS had higher IL-1A expression." (PMID 37740179, 2023). "Tumor cells produce chemokines (CXCL2-CXC motif chemokine ligand 2), cytokines (IL-6–interleukin 6), growth factors (TGF-transforming growth factor), and platelet-derived growth factor (PDGF), thereby stimulating the transformation of normal fibroblasts into activated CAFs." (PMID 37108109, 2023). "IL-6 has a key role in PDAC development and progression: it effects immune suppression in the tumor microenvironment and enhances angiogenesis, proliferation and migration of tumor cells." (PMID 36672313, 2023). "Elevated levels of IL-6, which is secreted by activated CAFs, particularly FAP + CAFs, contribute to the proliferation of immunosuppressive cells, impairment of anti-tumor cell functions, and ultimately, tumor progression and therapy resistance through various downstream signaling pathways." (PMID 37723510, 2023). "Additionally, it also controls the inflammatory response within the tumor microenvironment by reducing the expression levels of TNF-α, IL-1β, and IL-6." (PMID 37894468, 2023). "The treatment also reduced the IL-6 level in tumor tissues, but no synergistic effect was found with the combination therapy." (PMID 37397393, 2023). "The molecules secreted by both tumoral and non-tumoral cells, such as VEGF, FGF, EGF, IL6, TNFα, and immune checkpoint molecules, contribute to the crosstalk between the tumor and its microenvironment." (PMID 37958474, 2023). "TGF-β can increase the production of IL-6 and VEGF by tumor cells." (PMID 37033238, 2023). "In addition, tumour-infiltrating macrophages secrete inflammatory factors and cytokines, such as TGFβ, IL-6, IL-10, and tumour necrosis factor α (TNFα), which promote EMT, have been shown to enrich tumours with CSC-like properties." (PMID 37174052, 2023). "In turn, IL-6 secreted by activated fibroblasts boosted tumor-cell proliferation and chemoresistance, but not migration." (PMID 37173963, 2023). "IL-6 is also one of the main cytokines that bind to the IL-6 receptor to activate the STAT signaling pathway and can induce macrophages to differentiate into M2 type, thereby promoting the proliferation of tumor cells and resisting apoptosis." (PMID 36985801, 2023). "Besides, impressively decline in Th2 cytokines (interleukin (IL)−10, IL‐6, TGF‐β) and increase in Th1 cytokines (IL‐2, interferon (IFN)‐γ, IL‐12a) were noted in serums from tumor‐bearing mice post Pres and irradiation treatments." (PMID 37875395, 2023).